CRP (C-reactive protein)
Diseases named in the same sentence as CRP in open-access papers (continued):
Sharing a sentence is not in itself a finding about the gene and the disease.
bacterial pneumonia (continued). "Among respiratory diseases, CRP levels have primarily been studied in lung diseases and have been reported to be elevated in bacterial pneumonia, bronchopneumonia, and aspiration pneumonia." (PMID 38250933, 2024). "Previously, characteristics of blood test findings have been described in specific respiratory diseases, such as elevated white blood cell and CRP levels in bacterial pneumonia and aspiration pneumonia." (PMID 38250933, 2024). "It is interesting to note that the same factors influencing antibiotic therapy are found in the items (CRP, age, fever, chest X-ray, neutrophil) used to establish a bacterial pneumonia score published in 2021 by Moreno." (PMID 37110306, 2023). "Bacterial pneumonia is the infectious inflammation of lung parenchyma leading to cough, fever, tachypnea, chest retraction, leukocytosis, hypoxia, elevated C-reactive protein, and lung infiltration on chest X-ray." (PMID 37081543, 2023). "The aim of this prospective observational study was to determine the clinical utility of PCT and CRP as biomarkers for canine bacterial pneumonia." (PMID 38053473, 2023). "C‐reactive protein (CRP) is a biomarker commonly used in canine bacterial pneumonia to support diagnosis and monitoring." (PMID 38053473, 2023). "The present study showed significant increases in serum concentrations of CRP >10, >20, >40, >80, and >100 mg/dl in patients with bacterial pneumonia." (PMID 38585537, 2023). "Twenty-five children showed both increased C-reactive protein amounts and X-ray thickening suggestive of bacterial pneumoniae." (PMID 36992426, 2023). "A CRP level above 40 mg/L has a sensitivity of 70% to 73%, and a specificity of 90% to 65% in diagnosing bacterial pneumonia." (PMID 37296721, 2023). "The sensitivity and specificity of the CRP test in bacterial pneumonia is relatively low, and CRP values above the normal range can be due to other illnesses." (PMID 37107150, 2023). "Another study that evaluated different respiratory diseases in dogs detected the highest CRP values in patients with bacterial pneumonia, with a median of 121 mg/L." (PMID 36713872, 2022). "For the purposes of differentiation between viral and bacterial pneumonia, the CRP showed a higher AUC than the procalcitonin (AUC = 0.675 vs. AUC = 0.589, respectively)." (PMID 36233374, 2022). "Although CRP indicates bacterial pneumonia, their value is limited in predicting the severity of CAP in the early stage." (PMID 36123652, 2022). "The results showed that serum SAA, PCT and CRP were highly expressed in children with respiratory tract infection in China, and the expression level was the highest in children with bacterial pneumonia." (PMID 35775463, 2022). "CRP typically induced by IL-6, IL-1β and TNF-α CRP has been identified in bacterial pneumonia patients as early as the 1930s." (PMID 36211412, 2022). "Most patients exhibit normal levels of C-reactive protein (CRP) and diagnostic differentiation from bacterial pneumonia remains challenging." (PMID 32912295, 2020). "According to a meta-analysis published in 2008, children with bacterial pneumonia had a significantly higher probability of having CRP values of 35–60 mg/L on admission, compared to children with viral pneumonia." (PMID 32637387, 2020). "He developed hypokalemia, hypocalcemia, low white blood cell count, elevated C-reactive protein level, mixed acidosis, hepatic and kidney damage, thickening of the jejunal wall, and lung atelectasis, which served as a basis for the ensuing bacterial pneumonia." (PMID 32948124, 2020). "For a CRP threshold of 72 mg/L, the AUC of ROC was 0.82 for discriminating definite bacterial pneumonia from presumed viral pneumonia." (PMID 30940126, 2019). "Among the 230 patients who developed viral or bacterial pneumonia as severe complications, the average level of CRP (± SD) was 75 ± 31 mg/L." (PMID 30288556, 2019).
bacterial pneumonia (continued). "CRP ≥ 40 mg/L, CRP ≥ 60 mg/L and CRP ≥ 100 mg/L cut-off had sensitivity of 83, 75 and 67%, respectively for differentiating definite bacterial pneumonia from presumed viral pneumonias." (PMID 30940126, 2019). "In humans, CRP is the most elevated APP in bacterial pneumonia but only a little increase of CRP is found in severe viral acute respiratory syndrome, while the greatest increase can be seen in other APP, for example, alpha-1-antitrypsin (AT)." (PMID 31049027, 2019). "High CRP (≥100 mg/L) was very common among the CXR-AC cases with confirmed bacterial pneumonia (71%) and uncommon (4%) among RSV pneumonia cases." (PMID 28575375, 2017). "Even in those detecting a difference, overlapping CRP distributions indicate imperfect specificity for bacterial pneumonia." (PMID 28575375, 2017). "CRP levels among controls can be used to determine a reasonable minimal threshold to serve as a reliable biomarker for bacterial pneumonia." (PMID 28575375, 2017). "Among the confirmed bacterial pneumonia cases, those confirmed for either Spn or Hinf had higher CRP (84% CRP ≥40 mg/L and 74% CRP ≥100 mg/L) than cases confirmed for other bacteria (69% CRP ≥40 mg/L, P = .18 and 45% CRP ≥100 mg/L, P = .02)." (PMID 28575375, 2017). "The role of CRP in discriminating between bacterial pneumonia and viral pneumonias other than RSV warrants further study." (PMID 28575375, 2017). "Patients with bacterial pneumonia had significantly elevated CRP levels (214 mg/L; IQR = 81 to 335) compared with patients with isolated H1N1 pneumonia (108 mg/L; IQR = 50 to 213, p = 0.003)." (PMID 24612487, 2014). "It is difficult to explain with accuracy why mixed CAP showed higher CRP levels than both viral and bacterial pneumonias." (PMID 25073709, 2014). "In this limited number of patients, soluble CD14 serum levels tended towards a higher sensitivity, specificity and diagnostic accuracy compared to CRP and WBC in the diagnosis of bacterial pneumonia." (PMID 20302606, 2010). "In conclusion, this study provides evidence of the potential utility of PCT and CRP to differentiate viral from invasive bacterial pneumonia in children free of P. falciparum in areas with high prevalence of HIV infection." (PMID 20976241, 2010). "CRP is commonly used to identify bacterial pneumonia in children and has been found to have a higher sensitivity and specificity for community-acquired pneumonia compared to WBC and ESR, especially at levels >60 mg/l." (PMID 20302606, 2010). "Serum PCT and CRP are independent predictors of bacterial pneumonia." (PMID 41509129, 2026). "C-reactive protein (CRP) and procalcitonin (PCT) are more useful biomarkers than white blood cell counts in differentiating bacterial pneumonia from other causes of respiratory distress, but sensitivity and specificity are only approximately 70% and 65% for CRP or PCT respectively." (PMID 39661638, 2024). "In patients with severe bacterial pneumonia, CRP levels can exceed 200mg/L." (PMID 38633749, 2024). "Additionally, there is sparse and diverging information in the literature on the level of CRP for the diagnosis of bacterial pneumonia in adults; some studies suggest 60 mg/L as cut-off and others use 100 mg/L." (PMID 37107150, 2023). "However, in our multivariate analysis, we included factors that are commonly elevated in bacterial pneumonia, i.e. white blood cell count, neutrophil count, and CRP, so we believe that we were able to reduce this effect statistically." (PMID 36653462, 2023). "However, approximately 23% of cases with confirmed severe or very severe bacterial pneumonia also had CRP <40 mg/L." (PMID 37275364, 2023). "More specifically, typical bacterial pneumonia is more likely to drive elevated WCC and CRP, however, elevated biomarkers can also be caused by viral pathogens, especially when disease manifestation is severe, leading to reduced specificity for bacterial infection." (PMID 36913404, 2023).
bacterial pneumonia (continued). "The predicted probability of typical bacterial pneumonia is almost doubled if the child has no breathing difficulty, and a moderately high CRP (40 mg/L) can be indicative for a bacterial cause." (PMID 36913404, 2023). "In the bacterial pneumonia group, there were significant and insignificant positive correlations between CRP and complement proteins C3 and C4, respectively, suggesting a potential role of CRP in activating the complement system during bacterial infection." (PMID 38585537, 2023). "In a total of 106 dogs, the 22 diagnosed with bacterial pneumonia experienced a significantly higher rise in CRP than dogs with other respiratory diseases (bacterial tracheobronchitis, idiopathic pulmonary fibrosis, chronic bronchitis, cardiogenic pulmonary edema, eosinophilic bronchopneumopathy)." (PMID 36290272, 2022). "Flu-like symptoms such as cough, sore throat, headache, myalgia, and prolonged fever were more common in SARS-CoV-2 CAP, whereas clinical findings suggestive of bacterial pneumonia such as dyspnea, leukocytosis with left shift, and increased C-reactive protein were more common in endemic HCoV CAP." (PMID 33444422, 2021). "As severe bacterial pneumonia and urosepsis in a hyperacute stage may present with cytopenia and normal CRP, normal CRP in an acute presentation should be cautiously interpreted." (PMID 32134948, 2020). "However, among CXR+ cases in both groups, the percentage with elevated CRP was higher among cases with CXR-AC than cases with CXR-OI: 85% vs 50% (P = .004) among confirmed bacterial pneumonia cases and 31% vs 18% (P = .01) among RSV pneumonia cases." (PMID 28575375, 2017). "Among HIV-positive cases, differences were less extreme but trends were similar, though small numbers limit interpretation: 69% of 26 cases with confirmed bacterial pneumonia had CRP ≥40 mg/L compared with 45% of 11 cases with RSV pneumonia (data not shown; P = .41)." (PMID 28575375, 2017). "Though, because the controls selected for testing in our study deliberately targeted those thought to have a higher likelihood of elevated CRP, an analysis comparing controls to cases would have been biased by underestimating specificity for bacterial pneumonia." (PMID 28575375, 2017). "Several studies have evaluated the utility of CRP testing in TB, demonstrating a lower median CRP in TB compared to bacterial pneumonia and that the addition of CRP testing to clinical assessment can aid the management of HIV positive patients in a high TB incidence setting." (PMID 27287260, 2016). "In a related study, Cole and Bose used a CRP of > 40 mg/L as a proxy for bacterial pneumonia." (PMID 22316073, 2012). "In addition, combined use of both PCT and CRP may further improve the capability to predict bacterial pneumonia early." (PMID 37510807, 2023). "Thus CRP alone is insufficient for diagnosing bacterial pneumonia." (PMID 37275364, 2023). "Increased levels of inflammatory cytokines, C-reactive protein, and fibrinogen, along with increased myocardial demand for oxygen and lowered blood oxygen levels, are among the factors that have been reported to lead to cardiac dysfunction in patients with bacterial pneumonia." (PMID 30618794, 2018). "In this study, the predictive ability of adipic acid and glycineamideribotide for bacterial and non-bacterial pneumonia was far superior to clinical indicators such as WBC, NEU%, PCT, and CRP." (PMID 39283042, 2024). "Laboratory tests, specifically elevated WBC, ESR, CRP and PCT, were significantly better at predicting bacterial pneumonia than were signs and symptoms, with area under ROC of between 0.60 and 0.65." (PMID 39661638, 2024). "Cut off values that predicted bacterial pneumonia as the Consensus Diagnosis were ESR ≥ 47 mm/hour, CRP ≥ 42 mg/L and procalcitonin ≥0.85 ng/m." (PMID 39661638, 2024). "For the severity and prognosis of bacterial pneumonia, in conjunction with other clinical examination, PCT levels have been shown to be more advantages than CRP." (PMID 37465762, 2023).
bacterial pneumonia (continued). "Considering the significance of the possible fatal error of a false diagnosis for patients with bacterial pneumonia, the role of PCT and CRP as independent biomarkers to exclude bacterial infection of the lower respiratory tract is limited." (PMID 31183362, 2019). "CRP and WBC levels were in most cases high and patients were treated with antibiotics because of suspected bacterial pneumonia." (PMID 31750306, 2019). "The value of sCD14 in serum and BALF compared to CRP and WBC for diagnosing bacterial pneumonia in children." (PMID 20302606, 2010). "In contrast, WBC, CRP and LDH were found to be highest in bacterial pneumonia." (PMID 34244563, 2021). "This study also showed that elevation of CRP with the presence or absence of clinical symptoms, such as fever (≥38 °C) or the absence of rhinorrhea differentiates bacterial pneumonia from viral pneumonia better than CRP alone." (PMID 31918745, 2020). "An abnormal chest radiograph was associated with CRP ≥40 mg/L among HIV-negative cases with RSV pneumonia (24% of CXR+ vs 12% of CXR-normal cases, P < .001) but not cases with confirmed bacterial pneumonia (77% vs 75%)." (PMID 28575375, 2017). "Nevertheless, the 3% found with CRP ≥40 mg/L demonstrates the lack of perfect specificity of this marker for identifying bacterial pneumonia." (PMID 28575375, 2017). "Among 119 HIV-negative cases with confirmed bacterial pneumonia, 77% had CRP ≥40 mg/L compared with 17% of 556 cases with RSV pneumonia (P < .001)." (PMID 28575375, 2017). "Among 119 HIV-negative cases with confirmed bacterial pneumonia, 77% had CRP ≥40 mg/L compared with 17% of 556 RSV pneumonia cases." (PMID 28575375, 2017). "Our findings confirm the current consensus in the literature, which is that while CRP is elevated in bacterial pneumonia, CRP alone is not sufficient for diagnosing bacterial pneumonia." (PMID 28575375, 2017). "The clinical picture of acute exacerbation is not easily distinguished from bacterial pneumonia (elevation of c-reactive protein and pulmonary infiltrates)." (PMID 27729035, 2016). "Measurement of PCT, CRP, and WBC may be useful to predict typical bacterial pneumonia, since elevated levels were observed in comparison to atypical bacterial and viral pneumonia." (PMID 19594893, 2009). "They found that, with a cut-off point of 0.5 ng/mL, PCT but not CRP is able to help in the differentiation of typical bacterial pneumonia from atypical pneumonia." (PMID 20011658, 2009). "The chest radiograph and non-specific laboratory markers such as C-reactive protein, procalcitonin and white blood cell count provide some guidance, but the results overlap significantly in viral and bacterial pneumonia." (PMID 18644109, 2008). "Although several included studies reported CRP values for non-melioidosis infections (e.g., leptospirosis, scrub typhus, bacterial pneumonia), the heterogeneity of comparator groups, inconsistency in reporting units, and variation in assay methodology precluded formal pooled analysis." (PMID 41010302, 2025). "The positive effect of the wide dynamic range of the method on bacterial-viral differential diagnostics could be seen when the minimum value of the bacterial pneumonia group was used as an alternative cutoff value (0.36 for FCBI-index, 14 mg/L for CRP, and 28 ng/L for PCT) in patients with RTI." (PMID 34844193, 2021). "Another limitation is that we did not have data on other aetiological agents than influenza A and B. We cannot rule out that a clinically missed diagnosis of bacterial pneumonia could explain single high CRP concentrations." (PMID 33174788, 2020). "The plasma concentrations of Lpc-2, CRP, and vWF in children with a positive blood culture or with “end point” consolidation on their chest radiograph (probable bacterial pneumonia) were significantly higher than in children with no consolidation and a low white blood cell count (P < .01)." (PMID 24696240, 2014).
bacterial pneumonia (continued). "Our aims in the present study were to test the utility of PCT in the diagnosis of bacterial pneumonia in patients admitted to the ICU during the 2009 H1N1 influenza pandemic, including its performance in important clinical subgroups, and to compare its performance with CRP." (PMID 24612487, 2014). "For example, PCT and CRP levels were higher in patients with bacterial pneumonia infected with Gram-negative bacteria than in those infected with Gram-positive bacteria; this finding could aid clinicians in determining the appropriate use of antibiotics as a supplementary means." (PMID 32908505, 2020). "In cases when a culture is negative, we rely on high neutrophil counts, elevated CRP levels, and CXR findings, which are highly suggestive of bacterial pneumonia." (PMID 36291392, 2022). "Some studies showed that WBC and CRP were increased significantly in individuals with bacterial pneumonia, compared with viral pneumonia; however, in another study, WBC count and CRP levels were not different between viral and non-viral CAP." (PMID 25531901, 2014). "Although data regarding the ability of CRP and PCT testing to differentiate bacterial from viral or noninfectious illness are heterogeneous, these investigations are limited by the lack of a reference standard for diagnosis of bacterial pneumonia." (PMID 34817224, 2021).